IL6 (interleukin 6)
Diseases named in the same sentence as IL6 in open-access papers (continued):
Sharing a sentence is not in itself a finding about the gene and the disease.
rheumatoid arthritis (continued). "It has been reported that in rheumatoid arthritis, the blood levels of IL-6 and TNF-α increase." (PMID 36601050, 2022). "Both IL-1 and IL-6 are involved in the pathogenesis of rheumatoid arthritis (RA)." (PMID 36676031, 2022). "IL-6 and IL-8 are the major inflammatory regulators in rheumatoid arthritis." (PMID 36278189, 2022). "The complex formed by IL-6, soluble IL-6 receptor and glycoprotein 130 (gp130) plays critical roles in the inflammatory pathways during the development of various autoimmune diseases, such as chronic inflammatory bowel disease, rheumatoid arthritis and asthma." (PMID 36561343, 2022). "In addition, IL-6 was found to be involved in the pathogenesis of rheumatoid arthritis and osteoarthritis." (PMID 34986839, 2022). "In addition, VEGF has proinflammatory and antiapoptotic roles in the pathogenesis of rheumatoid arthritis, and induces tumor necrosis factor-α and interleukin 6 from mononuclear cells in the synovial fluid of patients with rheumatoid arthritis." (PMID 36551311, 2022). "However, increased IL-6 suggests potential exacerbation of IL-6-mediated diseases, such as rheumatoid arthritis." (PMID 35265152, 2022). "Anti-inflammatory biologic agents, including but not limited to TNF-α inhibitors (e.g., adalimumab), interleukin-1 (IL-1) inhibitors (e.g., canakinumab), and IL-6 inhibitors (e.g., tocilizumab), have been used in treating rheumatoid arthritis (RA) and other inflammatory diseases." (PMID 35887724, 2022). "IL-6 may participate in the pathogenesis of rheumatoid arthritis (RA), including osteoporosis, not only in the inflamed joints but also in the whole body." (PMID 35905126, 2022). "Importantly, anti-IL-6 treatments are already in common clinical usage for the treatment of rheumatoid arthritis and have shown promising pain relief in a case report in FD; a clinical trial is ongoing (ClinicalTrials.gov identifier: NCT01791842)." (PMID 35262711, 2022). "Decreases TNF-α and IL-6 contents in the serum; prevents the synovial hyperplasia and inflammatory cell infiltration of the mouse ankle joint; and exerts a certain therapeutic effect on rheumatoid arthritis." (PMID 35566359, 2022). "A recent study showed that some enzoxazole derivatives act as TLR9 inhibitors with moderate to excellent activity in short term suppression of IL-6, suppression of IL-6 release from lymph nodes, indicating their potential as therapeutic agents for rheumatoid arthritis." (PMID 35566047, 2022). "IL-6 is involved in the pathological process of various clinical diseases, including bacterial infection, neonatal sepsis, respiratory infections, enteritis, rheumatoid arthritis, and other acute or chronic inflammatory diseases." (PMID 35323499, 2022). "IL-6 is also known as one of the most proinflammatory key factors in rheumatoid arthritis (RA)." (PMID 35890286, 2022). "In line with the immunosuppressive therapy approach, further studies have shown that targeted therapy reduced cardiovascular mortality in rheumatoid arthritis (IL-6, TNF-α, and IL-17A cascades), lupus erythematosus (IL-17A signaling) (Crispín and Tsokos, 2010), and psoriasis (IL-17/IL-23)." (PMID 36267276, 2022). "Tumor necrosis factor-α (TNF-α), interleukin-17 (IL-17), interleukin-6 (IL-6), interleukin-4 (IL-4) antibodies and other drugs have been proven useful in treating rheumatoid arthritis (RA), psoriasis, cytokine release syndrome (CRS), atopic dermatitis (AD) and other autoimmune diseases." (PMID 35844550, 2022). "These activities include hematopoietic activity, induction of B-cell, and nerve cell differentiation, while the overproduction of IL-6 may contribute to autoimmune disease, such as rheumatoid arthritis." (PMID 33435569, 2021).
rheumatoid arthritis (continued). "IPA identified the following top canonical pathways as significantly different: role of macrophages, fibroblasts, and endothelial cells in rheumatoid arthritis, serine biosynthesis, superpathway of serine and glycine biosynthesis I, IL-6 signaling, and ephrin receptor signaling." (PMID 33888746, 2021). "IL6 and IL8 could take part in a wide variety of inflammation-associated disease by inducing the inflammatory response, such as rheumatoid arthritis, ulcerative colitis, and acute pancreatitis." (PMID 34545276, 2021). "IL-6 is also involved in the pathogenesis of rheumatoid arthritis." (PMID 34064515, 2021). "Inhibition of class I/II HDACs or class III HDACs (Sirtuin) potently influences the activation of macrophages derived from the inflamed joints of patients with rheumatoid arthritis by inhibiting the production of proinflammatory factors, such as IL-6 and TNF-α, and inducing macrophage apoptosis." (PMID 34512154, 2021). "Tocilizumab, a humanized αIL-6R mAb, has been FDA approved for the treatment of several autoimmune diseases, including rheumatoid arthritis and systemic juvenile idiopathic arthritis, which demonstrates the feasibility and safety of inhibiting IL-6/STAT3 signaling systemically in human patients." (PMID 33411696, 2021). "Hesperidin intake has also led to a decrease in IL6 in a rheumatoid arthritis rat model." (PMID 33799833, 2021). "Moreover, repeated and prolonged exposure of synovial fibroblasts isolated from patients affected by rheumatoid arthritis led to a decreased production of IL-6." (PMID 34576295, 2021). "This hypothesis is also in line with other studies that have demonstrated a link between increased IL-6 expression and other chronic inflammatory diseases such as rheumatoid arthritis and inflammatory bowel disease." (PMID 34827409, 2021). "For example, we previously reported that IL-6, rather than leptin, was highly elevated in patients with rheumatoid arthritis, which correlated with the generation of pathogenic TFH cells in this autoimmune disease." (PMID 34031386, 2021). "Others with opposing direction of effect may reveal the potential adverse side effects for consideration in therapeutic development (e.g., with anti–IL-6 biologics for rheumatoid arthritis)." (PMID 33901562, 2021). "Similarly, in vivo, the knockdown of the EP4 receptor reduced circulating levels of IL-1β and IL-6 in a mouse model of rheumatoid arthritis." (PMID 33919366, 2021). "Furthermore, inhibition of the production of pro-inflammatory mediators including TNF-α and IL-6 by pseurotin A was observed in the synovial fluid of rats with rheumatoid arthritis." (PMID 33669259, 2021). "This has been reported for several chronicinflammatory diseases, such as cirrhosis, rheumatoid arthritis, andcancer.33−35 Cytokines, such as IL-6 and TNFα, were reportedto increase with cirrhosis progression which supports the link todownregulation of expression." (PMID 34428046, 2021). "Our previous work has successfully shown that targeting MAPK at TNF receptor-associated factor 6-mitogen-activated protein kinase 7 (TRAF6-TAK1) signalosome in rheumatoid arthritis synovial fibroblasts using EGCG effectively curbs the IL-1 induced IL-6 production." (PMID 33668085, 2021). "In fact, blockade of IL-6 is the mechanism of action of drugs such as tocilizumab, which is a recombinant humanised anti-human IL-6 receptor monoclonal antibody used in the treatment of rheumatoid arthritis." (PMID 34813621, 2021). "IL‐6 inhibitors such as tocilizumab are currently licenced for use in rheumatoid arthritis, juvenile arthritis and more recently have been under investigation for treatment of excessive inflammation in patients with severe acute respiratory syndrome coronavirus 2 infection." (PMID 33393675, 2021). "IL-6 antagonists such as Tocilizumab and Sarilumab, are approved for rheumatoid arthritis." (PMID 33790360, 2021).
rheumatoid arthritis (continued). "Indeed, inhibitory reagents for IL-1, IL-6, and TNFα provide clinical benefits for rheumatoid arthritis patients." (PMID 32079226, 2020). "Based on accumulating knowledge that some inflammatory cytokines, such as tumor necrosis factor α (TNFα), IL-1, and IL-6, play critical roles in the onset and progression of rheumatoid arthritis, specific inhibitory reagents for these cytokines have been developed." (PMID 32079226, 2020). "Furthermore, methotrexate was also previously reported to reduce the IL6 expression in rheumatoid arthritis patients." (PMID 33193304, 2020). "In addition, the concentration of IL-6 in the synovial fluid of patients with ReA was significantly higher than that of patients with rheumatoid arthritis, so it was proposed that the overproduction of IL-6 was related to the occurrence of ReA." (PMID 32039436, 2020). "Furthermore, piperine dose-dependently inhibited production of interleukin-6 and prostaglandin E2 in IL 1β-stimulated fibroblast-like synoviocytes from patients with rheumatoid arthritis." (PMID 33384596, 2020). "Interleukin-6 (IL-6) plays an essential function in the development of rheumatoid arthritis (RA), mainly through its proinflammatory effect, which may lead to joint destruction." (PMID 32292581, 2020). "Although it has been well known that high levels of IL-6 were detected in the joint fluid of rheumatoid arthritis patients and correlated with disease activity, the question whether this abnormality was a cause or result of disease remained a mystery." (PMID 32743515, 2020). "Also recently described were 40 unselected patients with unexplained torsade de pointes in whom IL‐6 concentrations were markedly elevated at levels equivalent to those with severe rheumatoid arthritis." (PMID 31538387, 2020). "In rheumatoid arthritis, IL-6 inhibitors are usually used as weekly or monthly injections." (PMID 32903555, 2020). "Indeed, elevated Il-6 levels were detected in rheumatoid arthritis, ulcerative colitis and Crohn’s disease." (PMID 32858892, 2020). "Furthermore, pre-diagnostic levels of plasma CRP and IL-6 are associated with a higher risk of Crohn’s disease; and TNFR2 level, a proxy for TNF-α, is associated with higher risk of rheumatoid arthritis up to 12 years prior to disease symptoms." (PMID 33259491, 2020). "Furthermore, also the skeletal muscles contribute to an anti-inflammatory milieu, and physical inactivity has been shown to be associated with an increased level of pro-inflammatory muscle markers (IL-1β, IL-6) in rheumatoid arthritis." (PMID 32577833, 2020). "The same was true for changes in serum protein levels of IL-6 in rheumatoid arthritis." (PMID 32106855, 2020). "Moreover, anti-IL-6 therapies have proven especially useful for example in treating rheumatoid arthritis in patients unresponsive to TNF inhibitors." (PMID 32411011, 2020). "Several epidemiological, as well as clinical studies, show that androgens attenuate the expression of inflammatory biomarkers including TNF-α, IL-1β, and IL-6 in various chronic inflammatory diseases like Crohn’s disease, psoriasis, rheumatoid arthritis and allergic asthma." (PMID 32120970, 2020). "As TNFα, IL-1, and IL-6 affect chondrocytes during rheumatoid arthritis development, their intracellular signaling pathways, including NF-ĸB and JAK/signal transducer and activator of transcription (STAT) signaling cascades, play a central role in destruction of cartilage tissues." (PMID 32079226, 2020). "For example, in rheumatoid arthritis, synovial fibroblasts stimulated with IL-17 and Cyr61 could over-proliferate and produce IL-6 and IL-8." (PMID 32733444, 2020). "To date, two monoclonal antibodies targeting either IL-6 (Siltuximab) or the IL-6R are approved for the treatment of the autoimmune Castleman disease and different forms of arthritis (Tocilizumab) or rheumatoid arthritis (Sarilumab)." (PMID 32456348, 2020).
rheumatoid arthritis (continued). "Moreover, in people with rheumatoid arthritis, IL‐6 inhibitor therapy results in rapid QTc shortening in 3–6 months." (PMID 31538387, 2020). "In IL-6-stimulating rheumatoid arthritis synovial fibroblasts, IGU reduced RANKL expression and RANKL/OPG ratio, and ERK 1/2 pathway may be involved in the regulation of RANKL expression by IGU." (PMID 32174824, 2020). "Biologics targeted to IL-6, such as tocilizumab, a humanized monoclonal antibody generated to the IL-6 receptor, are licensed for the management of active rheumatoid arthritis, juvenile idiopathic arthritis, and replasing or refractory giant cell arteritis (GCA)." (PMID 32903555, 2020). "In patients with rheumatoid arthritis (RA), IL-6 promotes angiogenesis in the affected joints and induces the differentiation of osteoclast precursor cells to mature osteoclasts, which results in the bone absorption and joint destruction typical of the disease." (PMID 32655577, 2020). "Furthermore, specific inhibitors of Janus kinases (JAKs), the downstream tyrosine kinases of IL-6, are also effective for rheumatoid arthritis patients." (PMID 32079226, 2020). "Interleukin 6 (IL-6) is a member of a family of cytokines known as gp130 cytokines and has been shown to be responsible for various musculoskeletal disorders, particularly rheumatoid arthritis (RA)." (PMID 31780931, 2019). "Also, RF positivity, SJC-28, TJC-28, CRP, erythrocyte sedimentation rate (ESR), uncarboxylated osteocalcin (ucOC), MMP-3, TNF-α, IL-6, disease Activity Score-28 for Rheumatoid Arthritis with ESR (DAS28-ESR) levels were alleviated." (PMID 31013659, 2019). "IL-6 signaling blockade has recently been proven to be therapeutically effective for a number of autoimmune and inflammatory disorders including rheumatoid arthritis, polymyalgia rheumatica, vasculitis, and Castleman disease, the diseases that exhibit aberrant IL-6 signaling pathway." (PMID 32117207, 2019). "Biological therapies targeting TNF-α, T cells, B cells, and various cytokines (including IL-6 and IL-1) have become essential for the treatment of rheumatic diseases [mainly rheumatoid arthritis (RA), ankylosing spondylitis, and psoriatic arthritis], as well as other immune-mediated diseases." (PMID 31134083, 2019). "The hypomethylation of the CpG motif in the promoter of IL-6 in rheumatoid arthritis (RA) is related to the overexpression of IL-6, which may be responsible for the pathogenesis of RA." (PMID 31117883, 2019). "Additionally, an alternative therapeutic application is to utilize CBCRs to target cytokines such as tumor necrosis factor-alpha (TNF-a) or IL-6, which are over-expressed in chronic inflammatory diseases (e.g., rheumatoid arthritis)." (PMID 31798579, 2019). "Moreover, cytokines produced in innate immune responses, such as TNFα, IL-6 and IL-1β are found at comparable levels in rheumatoid arthritis joint tissues, early OA and end-stage disease synovium." (PMID 31182934, 2019). "The anti-IL-6 receptor monoclonal antibody tocilizumab has been developed to block the trans-signalling of IL-6 activity, and it has been used as an immunosuppressive agent in treating chronic inflammatory diseases such as rheumatoid arthritis, juvenile idiopathic arthritis, and Castleman disease." (PMID 31780866, 2019). "IL-6 antibody therapy is currently approved for rheumatoid arthritis." (PMID 30453544, 2018). "This important event might be responsible for the induction of pro-inflammatory cytokines, including IL6 that can be induced by p50 and p65 in the rheumatoid arthritis pathology, as previously reported." (PMID 29801438, 2018). "Hence, IL-6 has emerged as a potential target for the treatment of autoimmune diseases, and IL-6-targeting therapies are licensed for rheumatoid arthritis and juvenile idiopathic arthritis." (PMID 30687710, 2018).
rheumatoid arthritis (continued). "The fact that IL-6 levels are higher in autoimmune diseases (e.g., rheumatoid arthritis) raises the hypothesis that increased IL-6 levels in OCD could favor the existence of an autoimmune etiological factor." (PMID 30096863, 2018). "Anti-IL-6 antibody has been approved for the treatment of patients with rheumatoid arthritis and may extend to patients with SLE or other conditions." (PMID 29441062, 2018). "Similarly, inflammatory cytokines such as IL-6, IL-18, and TNF-alpha, which are typically elevated in rheumatoid arthritis, have been associated with cardiovascular disease." (PMID 30886961, 2018). "Recent studies have shown that pharmacological blockade of IL-6 by a humanized anti-IL-6 receptor antibody is beneficial in patients with rheumatoid arthritis and JIA, suggesting that IL-6 might be an essential key cytokine in these diseases." (PMID 29675026, 2018). "The therapeutic index of rheumatoid arthritis (RA) may be improved with MTX therapy based on the IL-6 circadian rhythm." (PMID 27900440, 2018). "Consequently, high levels of both IL-6 and sIL-6R are markers for osteolytic disorders, such as rheumatoid arthritis." (PMID 30671025, 2018). "Furthermore, E. gracilis Z and paramylon exhibited symptom-relieving effects on rheumatoid arthritis and suppressed the secretion of cytokines IL-17, IL-6, and IFN-γ." (PMID 29389956, 2018). "A top pathway in both breeds is Role of Macrophages, Fibroblasts and Endothelial Cells in Rheumatoid Arthritis, which is a disease characterized by uncontrolled inflammation, and we observed upregulation of genes such as IL-1beta, IL-6, and IL-22 which are pro-inflammatory cytokines." (PMID 28166270, 2017). "Apoptotic CD4+ T cells from patients with rheumatoid arthritis and systemic lupus erythematosus were demethylated compared to healthy controls and favoured production of IL-6 when cultured with healthy macrophages, in contrast to the TGFβ produced in response to healthy AC." (PMID 28169339, 2017). "The aim of this study was to determine whether saliva interleukin-6 (IL-6) levels are elevated in patients with rheumatoid arthritis versus a control group and examine the possible relationship between the oral condition and the risk of RA." (PMID 28809379, 2017). "IL-6 was up-regulated in many diseases such as rheumatoid arthritis, multiple sclerosis, and lupus." (PMID 28149833, 2017). "Also in rheumatoid arthritis plasma and synovial fluid show increased IL-6 that is decreased by naproxen treatment], and in a cardiac myxoma patient with elevated IL-6." (PMID 28977822, 2017). "However, 2 clinical failures to find naproxen lowering of IL-6 (after spinal surgery and in rheumatoid arthritis) are of concern." (PMID 28977822, 2017). "In addition, enhanced IL-6 levels are observed in the joints and serum of rheumatoid arthritis patients." (PMID 28289415, 2017). "Both TNF-α and interleukin-6 (IL-6) play major roles in the pathogenesis of rheumatoid arthritis." (PMID 29140972, 2017). "Interestingly, it has been shown in rheumatoid arthritis that PD1+ TFH is maintained by plasmablasts by an IL-6-dependent positive feedback loop that should be investigated in IgG4-RD." (PMID 28348556, 2017). "Key words:Rheumatoid arthritis, periodontal disease, saliva, IL-6." (PMID 28809379, 2017). "Increased IL-6 in the body could induce the development of inflammatory diseases, such as rheumatoid arthritis and Crohn's disease, by its binding to IL-6R." (PMID 28953986, 2017). "IL-25, IL-6, and bioactive IL-17A were quantified in rheumatoid arthritis (RA) patient plasma." (PMID 28620392, 2017). "In addition, increased expression of IL-6 and IL-8 genes by IL-1β in our study support the inflammatory role of IL-1β as previous in vitro study observing enhanced IL-6 and IL-8 levels in rheumatoid arthritis synovial fibroblasts." (PMID 28068976, 2017).